PRL (prolactin)
Diseases named in the same sentence as PRL in open-access papers (continued):
Sharing a sentence is not in itself a finding about the gene and the disease.
corticotroph adenomas (17 papers, 2010 to 2025). "In the corticotropinoma group, the average number cells expressing ACTH was 51.1±17.4% (from 21% to 78%), and the average number cells expressing prolactin was 0.7±0.7% (from 0.1% to 1.8%)." (PMID 30719226, 2019). "Immunohistochemical reactions with antibodies against ACTH, PRL, GH, LH, and FSH were performed for comprehensive functional assessment in 46 corticotropinomas and 18 ACTH ectopic tumours (all EAS neoplasms were examined for CRH expression, none of them expressed FSH)." (PMID 23509456, 2013). "Similarity between corticotropinomas and ectopic ACTH-secreting tumours included their ability to express not only ACTH (or CRH in EAS neoplasms), but also two or more pituitary tropic hormones (GH, PRL, LH, and FSH) and proangiogenic markers (CD31 and VEGF), with equal frequency." (PMID 23509456, 2013).
endometrial cancer (17 papers, 2018 to 2025). Primary or metastatic malignant neoplasm involving the endometrium (mucous membrane that lines the endometrial cavity). "Human PRL (hPRL) expression has been reported to be upregulated in endometrial cancer (EC) and is associated with poor survival outcomes." (PMID 35820883, 2022). "PRL has been also proposed as biomarker for endometrial cancer, as it resulted to be the stronger discriminative biomarker for endometrial cancer with high diagnostic power even in the early stage in women with endometrial cancer I-III stage." (PMID 33162942, 2020). "PRL-signaling is upregulated in numerous hormone-dependent cancers including breast, prostate, ovarian, and endometrial cancer." (PMID 36714582, 2022). "Briefly, preincubation of PRL for 1 hour abrogated cisplatin-induced apoptosis of ovarian and endometrial cancer cells, as determined by Annexin V/PI staining." (PMID 36714582, 2022). "Circulating PRL levels have been found significantly higher in women with ovarian and endometrial cancer, as well as in patients with family history of ovarian and endometrial cancer, as compared to those with benign pelvic disease and healthy controls." (PMID 33162942, 2020). "On the other hand, miRNAs from the PR group potentially modulate members of the prolactin and estrogen signaling pathways in utero, embryo and post-embryonic development, and the genes involved in stem cell pluripotency and endometrial cancer." (PMID 31693318, 2020). "Serum PRL levels are reportedly increased in patients with cervical and endometrial cancers, so that to be proposed as biomarker for malignant uterine diseases." (PMID 33162942, 2020). "KEGG analysis identified 28 enriched pathways, including “transcriptional misregulation in cancer” (p = 0.0002), “metabolic pathways” (p = 0.0003), “endometrial cancer” (p = 0.0007), “prolactin signaling pathway” (p = 0.0012), and “MAPK signaling pathway” (p = 0.0110)." (PMID 38755543, 2024). "Furthermore, PRL is recognized as a biomarker of endometrial cancer development and poor prognosis, thereby it has been proposed as a potential therapeutic target, but clinical studies need to be carried out to understand its modulation." (PMID 34745013, 2021). "Circulating PRL levels are reportedly increased in patients with cervical or endometrial cancers, as well as uterine premalignant lesions, and might be used as discriminative biomarker in patients with uterine cancers." (PMID 33162942, 2020). "Furthermore, prolactin (PRL) signalling, identified here through pathway analysis, is upregulated in numerous hormone-dependent cancers including ovarian, breast, prostate and endometrial cancer and is linked to cancer via activation of JAK/STAT, AKT and MAPK pathways." (PMID 39285292, 2024). "This work aims to review the most important findings regarding the PRL/PRLR axis in cervical, ovarian, and endometrial cancers and its molecular mechanisms to support carcinogenesis." (PMID 34745013, 2021). "As for cervical cancers, no direct action of dopamine agonists on PRL synthesis and release from endometrial cancers has been documented." (PMID 33162942, 2020).
Menstrual disorder (17 papers, 2013 to 2025). Category of disorders related to menstruation. "Hormone levels FSH, LH, and prolactin were associated with menstrual disorders in WWoE (p < 0.05)." (PMID 36204000, 2022). "Gonadal axis hormone recovery after surgery proved less satisfactory, yet the prolactin relief rate at 77.4% offers sustained alleviation for symptoms like menstrual disorders and gonadal dysfunction." (PMID 37964947, 2023). "In fact, patients who consumed risperidone and showed menstrual disorders had a significant increase in serum PRL levels, showing a correlation between the incidence of elevated PRL and menstrual disorders." (PMID 32373066, 2020). "Significantly higher levels of LH and TSH and lower levels of prolactin were found in women with menstrual disorders compared to those with normal menstrual cycles." (PMID 28546817, 2016). "Hypersecretion of PRL has a variety of manifestations, including menstrual disorders in women, and our findings concurred with those of previous investigations." (PMID 25506361, 2014). "Menstrual disorders and visual field defects were more common in patients in the CD + PRL group than in patients in the CD group (P = 0.027 and 0.021, resp)." (PMID 25506361, 2014). "Some researchers estimated the prevalence of menstrual disorders in psychotic females on prolactin raising antipsychotic therapy, around 15–50%." (PMID 24490071, 2013). "In the case of premenopausal women, elevated prolactin levels may manifest themselves only as libido disorders, menstrual disorders or problems in becoming pregnant." (PMID 38429692, 2024). "It should be mentioned that at higher PRL levels more profound menstrual disorders were observed." (PMID 33426414, 2020). "Peripheral blood with a concentration of PRL is one of the contributors to menstrual disorders." (PMID 24834101, 2014). "Hormones like progesterone, luteinizing hormone and prolactin play pivotal roles in maintaining normal menstruation in women, and their imbalances could lead to menstrual disorders, which might contribute to the development of PMS or mediate some of the neuropsychiatric symptoms associated with PMS." (PMID 37854248, 2023). "In WWE without menstrual disorders, topiramate was associated with higher prolactin levels." (PMID 36204000, 2022). "This study aimed to investigate the effect of the COVID-19 virus on menstrual disorders, anti-Mullerian hormone (AMH), thyroid peroxidase (TPO), thyroid stimulating hormone (TSH), and prolactin levels in women with COVID-19 disease." (PMID 39906086, 2024). "The current study aimed to assess the menstrual disorder and the AMH, TSH, TPO, and prolactin levels in female patients with COVID-19." (PMID 39906086, 2024). "Compared with the group with menstrual disorders, the average level of both WWE and WWoE reproductive hormones (FSH, LH, and prolactin) in the group without menstrual disorders was lower, with estradiol being the only exception." (PMID 36204000, 2022). "The studied workers were divided into two groups of shift workers and non-shift workers and were compared in terms of the frequency of menstrual disorder (short-term cycle, long-term cycle, irregular cycle and bleeding during menstrual cycle) as well as hormonal values (FSH, LH, TSH, and Prolactin)." (PMID 23618486, 2013). "In WWE without menstrual disorders, topiramate was connected to higher prolactin levels." (PMID 36204000, 2022).
non-alcoholic fatty liver disease (17 papers, 2019 to 2025). "A systematic review and meta‐analysis revealed that low PRL level in T2D patients is associated with development of non‐alcoholic fatty liver diseases suggesting that PRL has a protective effect against the pathogenesis of non‐alcoholic fatty liver diseases." (PMID 39663784, 2024). "PRL may have a role also in intrahepatic lipid storage since circulating PRL has been demonstrated to be lower in patients with non-alcoholic fatty liver disease (NAFLD) compared to healthy controls." (PMID 36237192, 2022). "A recent clinical study into the role of PRL in the development of non-alcoholic fatty liver disease (NAFLED) suggested that there was a negative association between PRL and the presence of NAFLED." (PMID 33716958, 2021).
acne (16 papers, 2015 to 2025). An inflammatory process of the sebaceous glands which is characterized by comedones, nodules, papules and/or pustules on the skin. "That latter observation is particularly interesting, since it suggests that PRL can locally stimulate androgen metabolism, which is of potential significance not only in acne but also in androgenetic hair loss." (PMID 39000207, 2024). "Given that stress is a source of excess prolactin and thyroid hormones, the presence of receptors for these hormones in the skin may be a direct and indirect cause of excess sebum and sweat gland secretion, which would result in increased acne." (PMID 36552842, 2022). "Clinically, hirsutism and acne were significantly more common in the PCOS with elevated PRL group than in the prolactinoma group, with 86.1% of PCOS patients exhibiting hirsutism (p < 0.001) and 22.2% reporting acne (p = 0.006)." (PMID 40399716, 2025). "In this case, the patient exhibited mildly elevated prolactin levels alongside symptoms such as acne, blurred vision, and occipital headaches." (PMID 40656428, 2025). "Nevertheless, PRL is often included in an androgen work-up in patients with acne, hirsutism, and menstrual irregularities and obesity." (PMID 39000207, 2024). "Isotretinoin, a mainstay of treatment for severe acne, has also been shown to decrease serum PRL concentrations." (PMID 39000207, 2024). "Practitioners should scrutinize the specific impaired sexual domains and their correlatedconditions in PCOS women, notably orgasm, acne, and prolactin level." (PMID 33497050, 2021). "Thecurrent study, which indicates the exclusively negativeeffect of prolactin level, acne, and marital duration onthe sexual function of infertile PCOS women, impliesthat interventions may need to be modified accordinglyto educate patients on how to manage their specificproblems." (PMID 33497050, 2021). "In trans AMAB people, an increase in prolactin levels was demonstrated, whereas the most common side effects in trans AFAB people were acne development, erythrocytosis, and unfavorable changes in lipid profile." (PMID 35407392, 2022). "Investigating the PRL level of PCOS women visiting a dermatologist for acne and/or hyperseborrhea, without menstrual disturbances, could be of interest in an upcoming study." (PMID 35250884, 2022). "However, the clinical symptoms including paramenia, hirsutism, and acne and the serum levels of E2, T, DHEAS, and PRL were not significantly different between these two groups." (PMID 36714563, 2022).
Adrenal insufficiency (16 papers, 2013 to 2025). Insufficient production of steroid hormones (primarily cortisol) by the adrenal glands. "In 2022, he continued to require increased doses of hydrocortisone for adrenal insufficiency, with stable prolactin levels." (PMID 41293361, 2025). "Repeat laboratory tests showed resolution of the patient's secondary adrenal insufficiency, normalization of serum prolactin, and an increase in serum gonadotropin concentrations to the postmenopausal range." (PMID 37908996, 2023). "Although prolactin levels appeared low, he was diagnosed with adrenal insufficiency." (PMID 41293361, 2025). "The normal findings on brain and pituitary MRI and the normal thyroid function tests and prolactin levels in our patient effectively ruled out pituitary or hypothalamic diseases as potential causes of the secondary adrenal insufficiency." (PMID 24616769, 2013). "In the presence of secondary adrenal insufficiency, a pituitary RMI with contrast agent (unless contraindicated) and tests of the other hormone axes (FSH, LH, FT4, TSH, prolactin, testosterone in males and estradiol in females, IGF-1) are recommended." (PMID 35407442, 2022). "Although TSH (thyrotropin), GH (growth hormone), PRL (prolactine) and gonadotropins’ levels alteration do not pose a threat in acute care, adrenal insufficiency and antidiuretic hormone secretion abnormalities may impact critical care management." (PMID 33371363, 2020).
Headache (16 papers, 2011 to 2025). Cephalgia, or pain sensed in various parts of the head, not confined to the area of distribution of any nerve. "In the current study, we compared the level of prolactin in migraineurs with age‐ and sex‐matched headache‐free subjects and investigated its association with the number of headache days." (PMID 37190874, 2023). "Proposed points of considerations for future studies of association between prolactin and migraine headache (or pain)." (PMID 34737888, 2021). "The findings suggest that there might be an association between increased prolactin concentrations and migraine headache induction and progression." (PMID 37190874, 2023). "Recently, it has been reported that neuronal activation in the hypothalamus regulates stress-induced headache behaviour, which is mediated by prolactin in female mice only." (PMID 38802819, 2024). "Since BMI can affect both prolactin levels and migraine headache, it was considered as a confounding factor." (PMID 37190874, 2023). "When prolactin is considered alongside androgen and ovarian hormones, pronociceptive headache states fueled by estrogen can recruit prolactin-induced sensitization to further advance chronic pain since estrogen increases PRL receptor expression." (PMID 37795389, 2023). "Likewise, patients with prolactinoma-associated headaches, which can involve different headache phenotypes (including cluster headache, trigeminal autonomic cephalalgias, short-lasting unilateral neuralgiform headache, and migraine with visual aura), also present with high serum levels of PRL." (PMID 36967387, 2023). "Further detailed and well‐designed studies are needed to confirm the importance of serum prolactin levels in the pathogenesis of migraine headaches." (PMID 37190874, 2023). "The Spearman's correlation test also showed significant correlations between the serum prolactin levels and the number of headaches days among migraineurs." (PMID 37190874, 2023). "Furthermore, hormone secretion imbalances related to the pituitary gland can also trigger headaches, such as changes in prolactin secretion." (PMID 40099826, 2025). "One of the strengths of the present study that sets it apart from other studies is that we evaluated the level of prolactin in the ictal and interictal periods in the EM group and compared the values with those of the CM group as well as with headache‐free controls." (PMID 37190874, 2023). "Given the variation in prolactin levels in serum during headache attacks, previous studies have suggested that prolactin may be involved in the mechanism of the attacks." (PMID 37190874, 2023). "However, studies have found that serum prolactin levels have increased in patients with headache, especially migraineand and surgical trauma can activate hypothalamus and pituitary." (PMID 38097947, 2023). "These included 18/22 cases with visual field and vision disorders; 19/25 cases with headaches; 11/15 cases where high baseline PRL returned to normal levels; 6/7 cases where elevated blood GH returned to normal levels; and 2/3 cases where elevated blood ACTH returned to normal levels after surgery." (PMID 28978177, 2017). "Finally, our results of the multivariable analysis indicated that rather than the prevalence of headaches at diagnosis or gonadotropin deficiency, only high baseline PRL values were independent risk factors for persistent DA dependence in the long term." (PMID 39904877, 2025). "The mean ± SD serum prolactin levels of the chronic migraineurs (1.82 ± 0.94) and those with ictal EM (1.93 ± 1.70) were comparable and were significantly higher than for interictal EM patients (0.82 ± 0.46) and the headache‐free control subjects (0.49 ± 0.15; p < .001)." (PMID 37190874, 2023). "The mechanism through which prolactin could affect headache attacks is unknown." (PMID 37190874, 2023).
Headache (continued). "High baseline PRL values (HR 23.9, 95% CI 1.0-593.7, p = 0.05), but not the presence of headache or male gender, were identified as independent predictors of long-term dependence on DAs." (PMID 39904877, 2025). "It was also found that interictal EM subjects out of the acute phase had higher levels of prolactin than the headache‐free subjects, but the difference between groups was not significant." (PMID 37190874, 2023). "Headache is more common in males (67-77% vs. 17-30% in females) and does not seem to be related to the tumor size or prolactin level." (PMID 21750634, 2011). "Moreover, it is not clear yet how altered PRL levels may influence different headaches (i.e., episodic and chronic migraine, tension-type headache, cluster headache) and possibly aura or prodromal symptoms." (PMID 36967387, 2023).
hepatitis B (16 papers, 2013 to 2026). "PRL is a growth regulator for cells of the immune system, and we showed that PRL mutations were associated with hepatitis B infection, suggesting that PRL might be implicated in the production of HBs-Ag." (PMID 24988079, 2014). "The target genes of downregulated DEmiRNAs were mainly related to the TGF-beta signaling pathway, Proteoglycans in cancer, Dorso-ventral axis formation, Hepatitis B, and Prolactin signaling pathway." (PMID 32925795, 2020). "HCC derived from hepatitis B infection demonstrated a significantly higher rate of OR8K3, PRL and RYR2 mutations (22% vs. 0%, 22% vs. 1%, 22% vs. 2%; p = 0.008, p = 0.022, p = 0.041, respectively)." (PMID 24988079, 2014). "To evaluate the diagnostic values of serum MCP-1 and prolactin in distinguishing HCC patients from non-HCC hepatitis B carriers in comparison with serum AFP, we performed the ROC curve analysis to determine the sensitivity and specificity of these three markers in the SGH cohort." (PMID 23874805, 2013). "KEGG enrichment analysis showed that the top five KEGG pathways with high counts included pathways in cancer, prolactin signalling pathway, EGFR tyrosine kinase inhibitor resistance, hepatitis B pathway, PI3K–Akt signalling pathway." (PMID 35287559, 2022). "The pathways mainly regulated by ZJP were pathways in cancer, Chagas disease, hepatitis B, the Toll-like receptor signaling pathway, influenza A, proteoglycans in cancer, the MAPK signaling pathway, HTLV-I infection, the PI3K-Akt signaling pathway, and the prolactin signaling pathway." (PMID 34484403, 2021).
Hirsutism (16 papers, 2005 to 2025). Abnormally increased hair growth referring to a male pattern of body hair (androgenic hair). "The differences of FSH, PCOS morphology, hirsutism and irregular mense between patients and normal women were statistically significant but testosterone, PRL, FBS, E2 and BMI differences between case and control groups were not significant." (PMID 26131012, 2015). "Moreover, in patients with PCOS with elevated PRL, statistically significant improvements in hirsutism scores were also observed with sufficiently long follow-up durations under CAB therapy." (PMID 40399716, 2025).